MUC20 (mucin 20, cell surface associated)
Description:
May regulate MET signaling cascade. Seems to decrease hepatocyte growth factor (HGF)-induced transient MAPK activation. Blocks GRB2 recruitment to MET thus suppressing the GRB2-RAS pathway. Inhibits HGF-induced proliferation of MMP1 and MMP9 expression.
Synonyms: MUC-20; KIAA1359; FLJ14408
Tractability: Antibody: UniProt places it where antibodies can reach, with high confidence; its Gene Ontology location is reachable by antibodies, with high confidence; UniProt predicts a signal peptide or a membrane-spanning region; the Human Protein Atlas places it where antibodies can reach.
Gene: Protein-coding gene on chromosome 3 (195,720,884 to 195,741,123, forward strand). Ensembl gene ENSG00000176945.
Subcellular location: Secreted; Apical cell membrane; Basolateral cell membrane; Cell projection, microvillus membrane
Subcellular location (Human Protein Atlas): Cytosol; Nucleoplasm; Plasma membrane; Predicted to be secreted
Pathways (Reactome):
Disease: Defective C1GALT1C1 causes TNPS; Defective GALNT12 causes CRCS1; Defective GALNT3 causes HFTC
Metabolism of proteins: O-linked glycosylation of mucins; Termination of O-glycan biosynthesis
Immune System: Dectin-2 family
Signal Transduction: MET activates RAS signaling
Gene Ontology:
Molecular function: identical protein binding
Biological process: hepatocyte growth factor receptor signaling pathway
Cellular component: basal plasma membrane; Golgi lumen; plasma membrane; apical plasma membrane; basolateral plasma membrane; extracellular region; microvillus membrane
Genetic constraint (gnomAD): Loss-of-function variants: 14 observed, 15.46 expected, observed/expected ratio (o/e) 0.91, 90% interval 0.6 to 1.41. The upper end of that interval is the gene's LOEUF score, 1.41, which puts it in group 5 of 6, group 1 being the genes least tolerant of losing a copy. Missense variants: 371 observed, 428.15 expected, observed/expected ratio (o/e) 0.87, 90% interval 0.8 to 0.94. Synonymous variants: 161 observed, 184.6 expected, observed/expected ratio (o/e) 0.87, 90% interval 0.77 to 0.99.
Homologues: Orthologues: macaque MUC20 (56% identical), dog MUC20 (38% identical), rat Muc20 (30% identical), mouse Muc20 (30% identical).
Diseases named in the same sentence as MUC20 in open-access papers:
MUC20 is named in the same sentence as 47 diseases in open-access papers, as found by Europe PMC text mining. Sharing a sentence is not in itself a finding about the gene and the disease. The quoted sentences say what the papers report.
colorectal cancer (7 papers, 2013 to 2023). A primary or metastatic malignant neoplasm that affects the colon or rectum. "On the other hand, the overexpression of MUC20 was associated with recurrence and poor outcome in patients with colorectal cancer." (PMID 26770020, 2015). "Overexpression of MUC20 was found to be a predictor of poor outcome and recurrence in colorectal cancer." (PMID 35501919, 2022). "Another study showed that MUC20 was overexpressed and significantly correlated with recurrence and death in colorectal cancer." (PMID 34651428, 2021). "It has been reported that MUC20 is oversynthesized in gastric, ovarian, endometrial, and colorectal cancer and predicts recurrence and poor outcome." (PMID 26770020, 2015). "MUC4 and MUC20 expression is increased in colorectal cancer vs normal mucosae (GSE40967, p < 0.01)." (PMID 30236127, 2018). "Whereas MUC5, MUC6, MUC16, and MUC20 are absent from the normal colon and are expressed in colorectal cancers." (PMID 36900282, 2023).
endometrial cancer (5 papers, 2012 to 2022). Primary or metastatic malignant neoplasm involving the endometrium (mucous membrane that lines the endometrial cavity). "High MUC20 expression is considered a factor that negatively influences 5‐year cancer‐specific survival rates and recurrence‐free survival in early‐stage endometrial cancer patients." (PMID 34651428, 2021). "MUC20 overexpression predicts poor prognosis in endometrial cancer and enhances EGF-triggered invasive behavior through activation of EGFR–STAT3 pathway." (PMID 23787019, 2013). "However, in endometrial cancer, MUC20 overexpression drives tumourigenesis, predicts poor survival, and EGF-induced malignant phenotypes were enhanced by activating the EGFR/STAT3 pathway." (PMID 36059804, 2022). "MUC20 has been reported to correlate with the progression of various cancers, and is an independent prognostic factor for the poor survival rates of ovarian and endometrial cancer." (PMID 36553184, 2022). "Overexpressed MUC20 activates the EGFR-STAT3 pathway, promotes epidermal growth factor receptor (EGF) expression, and induces a malignant phenotype of endometrial cancer." (PMID 36553184, 2022). "Data from these assays performed on a panel of endometrial cancers from AA and CA confirmed the array findings for IGF1R, MUC20, and RRAD, but interestingly, qRT-PCR utilizing primers targeted to PSPH did not." (PMID 22783543, 2012).
COVID-19 (4 papers, 2021 to 2025). A disease caused by infection with severe acute respiratory syndrome coronavirus 2. "By using the same approach, we also showed that age and mRNA expression of MUC1, MUC2, MUC4, MUC6, MUC13, MUC16, and MUC20 were the most accurate variables associated with the presence of COVID-19 among symptomatic patients (AUCROC = 91.8%; sensitivity: 90.6%; specificity: 93.3%)." (PMID 34448730, 2021). "The top molecules in the COVID-19 T1 and T2 data set with the greatest alteration in methylation compared to healthy controls included hypomethylated MUC20, VAV3, CCL20, and mir21 and hypermethylated GIT2, IFNGR2, FCER1G, and OLR1." (PMID 41227320, 2025). "Another example is MUC20, at which we identified a Neanderthal-introgressed eQTL that increases MUC20 expression in SARS-CoV-2-stimulated CD4+ T cells and decreases COVID-19 susceptibility." (PMID 37558883, 2023). "A strong positive correlation was also seen between MUC1 and MUC2 mRNA expression and between MUC16 and MUC20 mRNA expression and specifically in the mild COVID-19 patient group." (PMID 34448730, 2021). "MUC1, MUC2, MUC4, MUC16, and MUC20 mRNA expression strongly correlated with COVID-19 severity, of which MUC1 and MUC20 mRNA expression also associated significantly with age and MUC16 and MUC20 mRNA expression with sex." (PMID 34448730, 2021). "Likewise, an approximately 39 kb Neanderthal haplotype, spanning the MUC20 locus in Eurasians, contains the rs2177336-T allele that increases MUC20 expression in SARS-CoV-2-stimulated cells, particularly for CD4+ T cells, and decreases COVID-19 susceptibility." (PMID 37558883, 2023). "Nevertheless, we identified cases (for example, DR1, OAS1-3, TOMM7, MUC20) in which selection or archaic introgression contributed to changes in both SARS-CoV-2 immune responses and COVID-19 outcome." (PMID 37558883, 2023).
ovarian carcinoma (4 papers, 2018 to 2022). A malignant neoplasm originating from the surface ovarian epithelium. "MUC15 was reported to participate in cell adhesion to the extracellular matrix in cancers, while MUC20 was reported to promote aggressive phenotypes in the epithelial ovarian cancer." (PMID 36482940, 2022). "In ovarian cancer, overexpressed MUC20 activates integrin β1 signaling and promotes FAK phosphorylation." (PMID 36553184, 2022). "MUC20 is a small mucin (500 aa) mostly expressed in renal proximal tube and that is deregulated in several cancers such as colorectal or ovarian cancers where it favors aggressiveness." (PMID 30236127, 2018). "Although MUC20 has been reported to play important roles in endometrial and ovarian cancers and modulate the MET signalling cascade in IgA nephropathy, the function and expression of MUC20 in PDAC remain unclear." (PMID 29993037, 2018). "We identified the N-glycosylation of MUC15 and MUC20 in ovarian cancer cells; the potential of the MUC15 and MUC20 as the diagnosis marker remains to be investigated in the future." (PMID 36482940, 2022). "For example, previous research has identified a series of mucins aberrantly secreted by ovarian cancer cells, including MUC1, MUC2, MUC4, MUC13, MUC16, and MUC20." (PMID 36553184, 2022).
gastric cancer (3 papers, 2018 to 2024). A primary or metastatic malignant neoplasm involving the stomach. "We showed that the combination of MUC4, MUC16 and MUC20 signature is associated with statistically significant reduced overall survival and increased hazard ratio in pancreatic, colon and stomach cancer." (PMID 30236127, 2018). "(A) Overall survival of MUC4/MUC16/MUC20 high and low risk groups in bladder cancer, colon cancer, lung adenocarcinoma, lung squamous adenocarcinoma, skin cancer and stomach cancer." (PMID 30236127, 2018). "This combination is associated with a poorer overall survival in different cancers including pancreatic, colon and stomach cancers suggesting MUC4/MUC16/MUC20 as a poor prognostic signature for these cancers." (PMID 30236127, 2018). "Additionally, MUC20 in gastric cancer cells plays a significant role in maintaining mitochondrial homeostasis." (PMID 38370477, 2024). "Mucin 20 (MUC20) has been reported to play a role in cancer drug resistance, and MUC20 variant 2 has been shown to aggravate chemoresistance to cisplatin and paclitaxel in gastric cancer." (PMID 38439082, 2024). "Among them, MUC16 and MUC20 membrane-bound mucins and their combination MUC4/MUC16/MUC20 is associated with a poorer overall survival in different cancers including pancreatic, colon and stomach cancers suggesting MUC4/MUC16/MUC20 as a poor prognostic signature for these cancers." (PMID 30236127, 2018). "In terms of the mitochondrial pathway, gastric cancer cells use different mechanisms, such as cellular retinoic acid-binding protein 2 (CRABP2), Ajuba, and MUC20, to maintain mitochondrial homeostasis and resist apoptosis." (PMID 38370477, 2024). "Overall, we observed that MUC4/MUC16/MUC20 signature harbored an increased hazard ratio compared with MUC4 alone for pancreatic cancer and to a lower extent in bladder cancer, colon cancer, lung squamous cancer and stomach cancer." (PMID 30236127, 2018).
multiple myeloma (3 papers, 2021 to 2025). "For instance, eccDNA-mediated MUC20 regulation reduces multiple myeloma resistance to proteasome inhibitors by inhibiting apoptosis." (PMID 40303312, 2025). "We found that MUC20 expression was suppressed in CR myeloma cell lines." (PMID 34651428, 2021).
pancreatic cancer (3 papers, 2018 to 2022). "Large-scale genomic dataset analyses demonstrated that the synergistic effect of MUC4, MUC16, and MUC20 was linked to a statistically significant reduction in OS and elevated HR in colon, stomach, and pancreatic cancers." (PMID 36059804, 2022). "We analyzed MUC4, MUC16 and MUC20 expression in pancreatic tumor (T) and paired adjacent non tumoral tissues (ANT) from GSE28735 and GSE16515 (not shown) datasets." (PMID 30236127, 2018). "Scrutiny of the Oncomine database determined that both the Pei Pancreas and Badea Pancreas feature higher MUC20 mRNA expression in pancreatic carcinoma tissue compared with normal pancreas tissue (P < 0.01)." (PMID 29993037, 2018). "To examine whether MUC20 interacted with MET through this domain in pancreatic cancer cells, we constructed the same truncated MUC20." (PMID 29993037, 2018). "The IHC of tissue microarray confirmed that MUC20 was overexpressed in pancreatic tumours compared with the adjacent non-tumour tissue (P < 0.05)." (PMID 29993037, 2018).
Diabetes (2 papers, 2012 to 2021). "Specifically we examined the Insulin-like Growth Factor Receptor 1, (IGFR1) Mucin 20, (MUC20), Ras Related Associated with Diabetes, (RRAD), and the Phosphoserine Phosphatase (PSPH) genes using qRT-PCR." (PMID 22783543, 2012).
IgA nephropathy (2 papers, 2018 to 2021). "MUC20 is a member of the mucin gene family, and prior research has suggested that its production is correlated with the progression of IgA nephropathy and other renal injuries." (PMID 34651428, 2021).
mantle cell lymphoma (2 papers, 2021 to 2024). Mantle cell lymphoma is a rare form of malignant non-Hodgkin lymphoma affecting B lymphocytes in the lymph nodes in a region called the ``mantle zone''. "Phosphorylation is critical for MET activation, and decreased MUC20 expression is negatively associated with MET activation in PI-resistant mantle cell lymphoma." (PMID 38439082, 2024). "In contrast, our previous study revealed that MUC20 attenuates PI (carfilzomib, CFZ) resistance by regulating proteasome capacity via the MET proto-oncogene receptor, receptor tyrosine kinase (MET) pathway in mantle cell lymphoma." (PMID 38439082, 2024).
pancreatic ductal adenocarcinoma (2 papers, 2018 to 2024). An infiltrating adenocarcinoma that arises from the epithelial cells of the pancreas. "In contrast, a previous study revealed that MUC20 knockdown decreased MET phosphorylation in pancreatic ductal adenocarcinoma cells, suggesting that MUC20 might exert opposite effects on MET phosphorylation depending on the cancer type." (PMID 38439082, 2024).
renal carcinoma (2 papers, 2017 to 2022). A carcinoma arising from the epithelium of the renal parenchyma or the renal pelvis. "Lastly, MUC15 and MUC20 methylation also appears to be of interest beyond renal carcinomas." (PMID 28978023, 2017).
ulcerative colitis (2 papers, 2015 to 2021). An inflammatory bowel disease involving the mucosal surface of the large intestine and rectum. "It was reported that the expression of MUC20 was down-regulated in ulcerative colitis mucosa, and our results showed that the expression of MUC20 in the colon and ZO2 in the ileum were significantly lower in the diarrhea goats, which was consistent with the previous study." (PMID 33614759, 2021).
acute myeloid leukemia (1 paper, 2018). Acute myeloid leukemia (AML) is a group of neoplasms arising from precursor cells committed to the myeloid cell-line differentiation. "(B) Overall survival of MUC4/MUC16/MUC20 high and low risk group in liver and acute myeloid leukemia (AML)." (PMID 30236127, 2018).
adenoma (1 paper, 2025). A neoplasm arising from the epithelium. "Importantly, mucins in Smad4Δ/Δ adenomas were among the DEGs with Muc4, Muc20, Muc2 being upregulated and Muc6 being downregulated (padj p < 0.05)." (PMID 40348815, 2025).
carcinosarcoma (1 paper, 2013). A malignant tumor composed of a mixture of carcinomatous and sarcomatous elements. "In salivary gland carcinosarcoma, specific amplifications of MUC20 (in mesenchymal element) were observed using oligonucleotide microarray-based comparative genomic hybridization, implying its important roles in the development of carcinosarcomas." (PMID 23787019, 2013).
cervical cancer (1 paper, 2024). A primary or metastatic malignant neoplasm involving the cervix. "In cervical cancer, MUC1, MUC4 and MUC20 were reported to be overexpressed in the squamous type." (PMID 38702644, 2024).
chronic kidney disease (1 paper, 2026). Impairment of the renal function secondary to chronic kidney damage persisting for three or more months. "Targeting MUC20-related signaling pathways may offer therapeutic potential for kidney fibrosis and chronic kidney disease." (PMID 41695494, 2026).
clear cell renal cell carcinoma (1 paper, 2024). "In clear cell renal cell carcinoma, resting mast cells are positively correlated with MUC20 level in the tumor immune microenvironment, while MUC20 expression is negatively linked with activated CD4+ memory T cells." (PMID 38564630, 2024).
coinfection (1 paper, 2021). The simultaneous infection of a host by multiple pathogen species. "Furthermore, the occurrence of pulmonary fungal coinfection negatively correlated with MUC2 and MUC20 mRNA expression and specifically in the deceased patients." (PMID 34448730, 2021).
Crohn disease (1 paper, 2020). A gastrointestinal disorder characterized by chronic inflammation involving all layers of the intestinal wall, noncaseating granulomas affecting the intestinal wall and regional lymph nodes, and transmural fibrosis. "MUC12 and MUC20 are involved in the epithelial cell protection, and the significant downregulation of MUC12 and MUC20 in the colon and ileum has been detected in patients with Crohn’s disease." (PMID 31624342, 2020).
esophageal squamous cell carcinoma (1 paper, 2022). Esophageal squamous cell carcinoma (ESCC) is a type of esophageal carcinoma (EC) that can affect any part of the esophagus, but is usually located in the upper or middle third. "Low expression of MUC20 was significantly correlated with tumour regression grade in patients with esophageal squamous cell carcinoma treated with neoadjuvant cisplatin and paclitaxel chemotherapy." (PMID 35501919, 2022).
intestinal infection (1 paper, 2021). "The transmembrane mucin MUC20 was reported to be upregulated in the course of an intestinal infection or inflammation." (PMID 34685068, 2021).
lung adenocarcinoma (1 paper, 2018). A carcinoma that arises from the lung and is characterized by the presence of malignant glandular epithelial cells. "MUC20 is increased in lung adenocarcinoma vs normal samples (GSE30219, p < 0.05)." (PMID 30236127, 2018).
lung carcinoma (1 paper, 2020). "MUC20 and MUC3A co-mutated at the junction of the tumor and tumor tissues are mucin family genes that are involved in the development of various adenocarcinomas, including lung cancer." (PMID 33133167, 2020).
lupus (1 paper, 2022). "MUC20 transcript levels were increased with the progression of lupus in the kidneys of MRL/lpr lupus-prone mice." (PMID 35479093, 2022).
ovarian adenocarcinoma (1 paper, 2018). An adenocarcinoma that arises from the ovary. "MUC16 and MUC20 relative expression is increased in ovarian adenocarcinoma (GSE14407, p < 0.01 and p < 0.05 respectively)." (PMID 30236127, 2018).
parasite infection (1 paper, 2022). "We found TFF1-3, MUC1, MUC6, and MUC20 expression in the bovine abomasal organoids reported here, which is consistent with their feasibility as a relevant in vitro culture model for studying host responses to parasite infection." (PMID 35846775, 2022).
Sepsis (1 paper, 2023). Sepsis is defined as life-threatening organ dysfunction caused by a dysregulated host response to infection. "At the genetic level, seven susceptibility genes for sepsis in severe burn patients were found: DNAH11, LAMA2, ABCA2, ZFAND4, CEP290, MUC20 and ENTPD1." (PMID 36659877, 2023). "Through genomic analysis, we identified seven important susceptibility genes (DNAH11, LAMA2, ABCA2, ZFAND4, CEP290, MUC20 and ENTPD1) in patients with severe burn injuries complicated with sepsis." (PMID 36659877, 2023).
signet ring cell carcinoma (1 paper, 2024). A usually aggressive, poorly differentiated invasive adenocarcinoma characterized by the presence of malignant glandular cells in which the nucleus is pressed to one side by the presence of intracytoplasmic mucus. "To date, only one study has shown that MUC20 regulates apoptosis and pyroptosis in signet ring cell carcinoma cells." (PMID 38439082, 2024).